HK2 (hexokinase 2)
Diseases named in the same sentence as HK2 in open-access papers (continued):
Sharing a sentence is not in itself a finding about the gene and the disease.
Hyperglycemia (19 papers, 2019 to 2026). An increased concentration of glucose in the blood. "A decreased expression of HK2 in obese and diabetic patients was also found and it was proposed that adipose tissue HK2 loss contributes to the development of insulin resistance and consequently hyperglycemia." (PMID 39860248, 2025). "An example of a therapeutic agent that corrects HK2-linked metabolic dysfunction in hyperglycemia is the glyoxalase 1 (Glo1) inducer, optimized to a combination of trans-resveratrol (tRES) and hesperetin (HESP), or tRES-HESP." (PMID 38292764, 2023). "We propose that loss of adipose HK2 is a mechanism of diet-induced insulin insensitivity and hyperglycemia." (PMID 36920797, 2023). "In this study, we show that HFD causes hyperglycemia by inducing loss of HK2 specifically in adipose tissue." (PMID 36920797, 2023). "Our findings suggest that the physiological mechanism of HFD-induced inhibition of adipose ChREBP and lipogenesis, and consequently hyperglycemia, may be loss of HK2." (PMID 36920797, 2023). "Our findings suggest that HFD causes loss of adipose HK2 and thereby triggers hyperglycemia." (PMID 36920797, 2023). "To examine further the role of adipose HK2 in glucose homeostasis, and in particular the causality of HK2 loss in insulin insensitivity and hyperglycemia, we generated an adipose-specific Hk2 knockout (AdHk2KO) mouse in which the knockout was induced at 4–5 weeks of age." (PMID 36920797, 2023). "Thus, loss of HK2 expression upon obesogenic conditions is an adipose-specific, transient physiological response that correlates with hyperglycemia." (PMID 36920797, 2023). "Collectively, these data suggested that the upregulated expression of Hk2, Ppargc1a, Sorbs1, and Hmox1 might be implicated in the improvement of hyperglycemia and insulin resistance in the exercise GK rats." (PMID 31338039, 2019). "Our findings identify adipose HK2 as a critical mediator of local and systemic glucose homeostasis, and suggest that obesity-induced loss of adipose HK2 is an evolutionarily conserved mechanism for the development of selective insulin resistance and thereby hyperglycemia." (PMID 36920797, 2023). "In mouse models, hyperglycemia accelerates tumor growth, whereas treatment with the HK2 inhibitor lonidamine mitigates tumor progression in the hyperglycemic setting." (PMID 41951587, 2026). "Future studies should directly compare the effects of microglial‐specific versus neuronal‐specific HK2 manipulation in stroke models with comorbid hyperglycemia." (PMID 41254936, 2025). "Moreover, reduced HK2 expression has also been observed in obese and diabetic patients, suggesting that the loss of HK2 in AT may contribute to the development of insulin resistance and, thereby, hyperglycemia." (PMID 40227203, 2025). "The 42% increase in HK2 protein concentration of embryos in 30 mM glucose cultures is similar to the increase found in endothelial cells and fibroblasts in model hyperglycemia supporting glycolytic overload." (PMID 40867918, 2025). "Quantifying the precise contribution of HK2 to increased glycolytic flux during hyperglycemia will require a more precise estimate of basal white matter glucose concentration." (PMID 39314314, 2024). "This and related findings in Mexican cavefish and adipose tissue of obese patients suggest that diet-induced downregulation of adipose HK2 contributes to hyperglycemia." (PMID 36920797, 2023). "Can HFD-resistant HK2 expression in adipose tissue prevent diet-induced insulin insensitivity and hyperglycemia?" (PMID 36920797, 2023). "Studies of the sciatic nerve of healthy control and streptozotocin (STZ)-induced diabetic rats indicate a high glucose content of the nerve, indicating that HK1 and HK2 are saturated in both euglycemia and hyperglycemia." (PMID 38292764, 2023).
Hyperglycemia (continued). "HK2 has similar saturation characteristics, except that, in persistent hyperglycemia, it is stabilized to proteolysis by high intracellular glucose concentration, increasing HK activity and initiating glycolytic overload and unscheduled glycolysis." (PMID 38292764, 2023). "Although further study is required to link the R42H mutation to the hyperglycemic phenotype in Molino cavefish, the findings in Molino provide orthogonal evidence that the down-regulation of HK2 in mice is physiologically relevant in hyperglycemia." (PMID 36920797, 2023). "For therapeutics development, correcting the primary initiating step of dysfunctional glucose metabolism in hyperglycemia is likely the most effective pharmacological target, that is, dysregulation of HK2 expression." (PMID 38292764, 2023). "Further support for this hypothesis in explanation for embryonic dysmorphogenesis in hyperglycemia came from the effect of the addition of tRES + HESP, which counters HK2-linked unscheduled glycolysis and glycolytic overload in a high glucose concentration." (PMID 40867918, 2025). "According to the hypothesis, the abnormally high flux of glucose metabolism seen in hyperglycemia results from the stabilization of HK2 against proteolysis by high cellular glucose concentrations." (PMID 40867918, 2025). "Importantly, the HK1/HK2 ratio was positively correlated with resting glucose consumption (r = 0.63), and negatively correlated with the change in glucose consumption during hyperglycemia (r = −0.63)." (PMID 39314314, 2024). "The correlation between changes in glucose consumption and HK2 expression suggests that differences in enzyme kinetics may play a role in regional differences in the brain’s response to hyperglycemia." (PMID 39314314, 2024). "However, our findings on diet-induced HK2 downregulation provide important new insight on the development of diet-induced hyperglycemia." (PMID 36920797, 2023). "HK-2 Knockdown prevented high glucose concentration-induced increased consumption of glucose and MG formation, supporting a key role of increased HK-2 in metabolic dysfunction of ECs in model hyperglycemia." (PMID 31133647, 2019). "Predictions to be explored in the future are (i) the positive association of HK2 expression with clinical insulin resistance and (ii) glycolytic overload in cells other than hepatocytes and beta-cells with dominant GCK expression and increased intracellular glucose concentration in hyperglycemia." (PMID 38292764, 2023). "In the “HK2-linked glycolytic overload and unscheduled glycolysis” hypothesis, the cytoplasmic hyperglycemia-induced stabilization of HK2 to proteolysis provides the initiating mechanism of increased glucose metabolism, circumventing the substrate saturation of hexokinases." (PMID 35216280, 2022). "Additionally, we observed in 1BR.3.N WWOX OE cell line variant the reduction of PKM2 and LDHA protein expression in normoxia normoglycemia, the decrease of HK2 protein in normoxia hyperglycemia, and PKM2 reduction in hypoxia hyperglycemia condition relative to 1BR.3.N WT cell line variant." (PMID 35328751, 2022). "BeWo cytotrophoblasts exposed to hyperglycemia displayed increased mRNA expression of ACSL1, HSD11B2, RPS6KA5, and LAP3 and reduced mRNA expression of CYP2F1, and HK2, concomitant with increased levels of: lactate, malonate, and riboflavin metabolites." (PMID 36930661, 2023). "Mechanistically, following the increased activity of CD8+ T-cells, the level of IL-7 level is increased, which subsequently promotes glucose uptake by elevating glucose transporter 1 (GLUT1) and hexokinase 2 (HK2) levels, deteriorating hyperglycemia B." (PMID 32802890, 2020). "Simulations of glucose transport revealed that, unlike hexokinase 1, HK2 is not saturated at euglycemia, thus accommodating increased AG during hyperglycemia." (PMID 39314314, 2024).
Hyperglycemia (continued). "Our simulations of glucose transport showed that, unlike HK1, HK2 is not saturated at euglycemia and can accommodate increases in flux by upwards of 50% during hyperglycemia." (PMID 39314314, 2024). "First, unlike GLUT4, HK2 downregulation in adipose tissue correlates with HFD-induced hyperglycemia in mice." (PMID 36920797, 2023). "Unlike vascular cells, the intracellular concentration of glucose in myocytes and adipocytes is usually relatively low: HK1 is saturated by glucose euglycemia and hyperglycemia, whereas HK2 is not." (PMID 38292764, 2023). "Both HK1 and HK2 expessed in these cell types are saturated with glucose, and yet, the flux of glucose metabolism is increased without increased HK expression in hyperglycemia." (PMID 38292764, 2023). "It is the stabilization of HK2 to proteolysis and unscheduled glycolysis rather than mitochondrial superoxide overproduction that initiates metabolic dysfunction in hyperglycemia." (PMID 38292764, 2023). "In contrast, the observed reduction in Hexokinase-2 (HK2, the first enzyme in the placental glycolysis metabolic pathway) transcript abundance could indicate that glycolysis is down-regulated in trophoblasts exposed to hyperglycemia." (PMID 36930661, 2023).
liver fibrosis (18 papers, 2022 to 2025). "The involvement of HK2 in CCl4-induced liver fibrosis highlights its significance as a key player closely linked to the development of liver fibrosis." (PMID 41245305, 2025). "Subsequently, MIG1 reduced the transcription of LDHA and HK2, which blocked glycolysis-mediated macrophage M1 polarization to mitigate liver fibrosis-associated inflammation." (PMID 40864752, 2025). "The expression of HK2 is notably increased in HSCs and is strongly linked to the advancement of liver fibrosis." (PMID 41245305, 2025). "To summarize, this research emphasizes the crucial importance of HK2 in the metabolic changes linked to liver fibrosis, especially in the stimulation of HSCs." (PMID 41245305, 2025). "The results showed that compared with normal tissue, HK2 expression was significantly upregulated in fibrotic liver tissue (p < 0.05), indicating that HK2 may be associated with the progression of liver fibrosis." (PMID 41245305, 2025). "The targeted deletion of HK2 was shown to effectively curb liver fibrosis in both in vivo and in vitro conditions, suggesting HK2 as a viable therapeutic target for liver fibrosis." (PMID 41245305, 2025). "Previous studies have indicated that HK2 boosts aerobic glycolysis in HSCs, indicating its involvement in the advancement of liver fibrosis." (PMID 41245305, 2025). "In our study, however, HK2 emerged as a key regulator of macrophage glycolysis during liver fibrosis." (PMID 41208891, 2025). "With its participation in glycolysis and its ability to affect cellular energy dynamics, HK2 appears to be a promising target for treating liver fibrosis." (PMID 41245305, 2025). "Targeted knockdown of HK2 in HSCs can significantly reduce liver fibrosis, aligning with our findings." (PMID 41245305, 2025). "Transcriptomic sequencing analysis demonstrated a significant elevation in HK2 expression in liver fibrosis tissues in our study." (PMID 41245305, 2025). "The stellate-cell-specific or systemic deletion of HK2 to inhibit H3K18la can mitigate stellate cellular activation and liver fibrosis." (PMID 40331975, 2025). "As a key regulator of cellular energy metabolism, HK2 has gained considerable attention in the context of liver fibrosis." (PMID 41245305, 2025). "H3K18la is upregulated in activated HSCs, and either HSC-specific or systemic deletion of hexokinase 2 (HK2) inhibits hepatic fibrosis in vivo by reducing H3K18la expression, which is reversed by exogenously supplementing lactate." (PMID 40584617, 2025). "Targeting HK2 can inhibit the activation of hematopoietic stem cells and reduce liver fibrosis systemically, showcasing the potential of HK2 as an effective therapeutic target for liver fibrosis." (PMID 39278916, 2024). "During hepatic stellate cell activation, hexokinase 2 (HK2) has been found to induce liver fibrosis by promoting histone lactylation." (PMID 38993478, 2024). "When liver fibrosis is initiated in HSCs, the expression of a series of enzymes related to digestion, represented by hexokinase 2 (HK2), increases, resulting in the massive production of lactate." (PMID 38481814, 2024). "However, a comprehensive analysis of the role of HK2 in human liver fibrosis tissue remains incomplete." (PMID 41245305, 2025). "Our results suggest that HK2 is central to the pathogenesis of liver fibrosis and may be valuable as a therapeutic target and biomarker." (PMID 41245305, 2025). "Additionally, hexokinase 2-mediated gene expression via histone lactylation is crucial for hepatic stellate cells and liver fibrosis." (PMID 40612514, 2025). "Targeted inhibition of HK2 reduced H3K18la expression in HSCs and inhibited liver fibrosis." (PMID 40584617, 2025). "Additionally, proteomic analysis confirmed a significant elevation of HK2 in the liver fibrosis model (p < 0.05)." (PMID 41245305, 2025).
liver fibrosis (continued). "Importantly, a significant positive correlation was observed between HK2 and hepatic fibrosis (r = 0.08), as well as alanine aminotransferase (r = 0.26) and aspartate aminotransferase (r = 0.37)." (PMID 41245305, 2025). "Prior findings suggest that HK2 aggravates liver fibrosis in mice." (PMID 41245305, 2025). "HK2 is involved in activating HSCs, thus promoting the progression of liver fibrosis." (PMID 41245305, 2025). "In this study, we used transcriptomics and single-cell transcriptomics to comprehensively investigate the expression of the HK2 gene in liver fibrosis, its relevance to the clinic, and the possible pathways affected by the HK2 gene at the human, animal, and cellular levels." (PMID 41245305, 2025). "In the process of liver fibrosis, hexokinase-2 (HK2) inhibits the transcriptional activation of fibrosis-suppressing genes by promoting lactylation at histone H3K18 sites rather than acetylation, which reveals the competitive substitution mechanism of lactylation at acetylation modification sites." (PMID 40331975, 2025). "Furthermore, the upregulation of HK2 and the enhancement of glycolysis have been reported to play pertinent roles in the activation of HSCs and liver fibrosis, which is the main contributor to liver cirrhosis and HCC." (PMID 35429101, 2022). "It provided evidence that treating liver fibrosis might be effective by targeting HK2." (PMID 38317138, 2024). "The enrichment of DEGs in pathways such as focal adhesion and ECM-receptor interactions indicates that HK2 KO has a notable effect on ECM deposition, which is important in the development of liver fibrosis." (PMID 41245305, 2025). "We hypothesize that HK2 produces significant lactate, influencing ECM deposition, cell adhesion, and other pathways through lactylation, thereby promoting liver fibrosis." (PMID 41245305, 2025). "Deletion of the HK2 gene inhibits HSC activation, suggesting that targeting HK2 and H3K18 lactylation may represent a potential therapeutic approach for hepatic fibrosis." (PMID 40421024, 2025).
oral squamous cell carcinoma (18 papers, 2017 to 2025). "Tanshinone IIA inhibits the development and proliferation of oral squamous cell carcinoma cells by suppressing Akt-c-Myc signaling and HK2-mediated glycolysis by diminishing HK2 expression at the transcriptional level." (PMID 38255882, 2024). "Gastrodin overcomes cisplatin resistance in oral squamous cell carcinoma cells by inhibiting the Akt/HK2 axis." (PMID 39468027, 2024). "The present study demonstrated that cisplatin-resistant oral squamous cell carcinoma (OSCC) cells exerted a stronger glycolysis ability, which was associated with hexokinase 2 (HK2) overexpression." (PMID 37779163, 2023). "Notably, IGF2BP2 has been shown to stabilize HK2 mRNA, thereby promoting the Warburg effect and driving the progression of oral squamous cell carcinoma." (PMID 41394397, 2025). "Similarly, Tanshinone IIA has been found to reduce HK2-mediated aerobic glycolysis in oral squamous cell carcinoma." (PMID 40756987, 2025). "Furthermore, immunohistochemical analysis showed that HK2 is strongly detected in 4-NQO–induced mouse tongue neoplastic lesions compared with normal oral epithelium, as well as human oral squamous cell carcinoma." (PMID 32195170, 2020).